F2R (coagulation factor II thrombin receptor)
Description:
High affinity receptor that binds the activated thrombin, leading to calcium release from intracellular stores. The thrombin-activated receptor signaling pathway is mediated through PTX-insensitive G proteins, activation of phospholipase C resulting in the production of 1D-myo-inositol 1,4,5-trisphosphate (InsP3) which binds to InsP3 receptors causing calcium release from the stores (By similarity). In astrocytes, the calcium released into the cytosol allows the Ca(2+)-dependent release of L-glutamate into the synaptic cleft through BEST1, that targets the neuronal postsynaptic GRIN2A/NMDAR receptor resulting in the synaptic plasticity regulation (By similarity). May play a role in platelets activation and in vascular development. Mediates up-regulation of pro-inflammatory cytokines, such as MCP-1/CCL2 and IL6, triggered by coagulation factor Xa (F10) in cardiac fibroblasts and umbilical vein endothelial cells.
Synonyms: PAR-1; CF2R; PAR1; TR; HTR
Tractability: Small molecule: an approved drug acts on it; a structure with a bound ligand is known; a high-quality ligand is known; it belongs to a druggable protein family. Antibody: its Gene Ontology location is reachable by antibodies, with high confidence; UniProt places it where antibodies can reach, with medium confidence; UniProt predicts a signal peptide or a membrane-spanning region. PROTAC: ubiquitination databases record sites on it; a small molecule that binds it is known. Other modalities: a drug acting on it is in phase 2 or 3 trials.
Target class: Protease-activated receptor; Membrane receptor; Peptide receptor (family A GPCR); Family A G protein-coupled receptor
Chemical probes: BAY-386 (high quality), ML 161
Gene: Protein-coding gene on chromosome 5 (76,716,126 to 76,735,770, forward strand). Ensembl gene ENSG00000181104.
Subcellular location: Cell membrane
Pathways (Reactome):
Hemostasis: Regulation of clotting cascade; Thrombin signalling through proteinase activated receptors (PARs)
Signal Transduction: G alpha (q) signalling events; Peptide ligand-binding receptors
Gene Ontology:
Molecular function: protein binding; signaling receptor binding; thrombin-activated receptor activity; G protein-coupled receptor activity; G-protein alpha-subunit binding; G-protein beta-subunit binding
Biological process: cell-cell junction maintenance; connective tissue replacement involved in inflammatory response wound healing; negative regulation of cell population proliferation; phospholipase C-activating G protein-coupled receptor signaling pathway; platelet activation; positive regulation of apoptotic process; positive regulation of blood coagulation; positive regulation of canonical NF-kappaB signal transduction; positive regulation of cell migration; positive regulation of collagen biosynthetic process; positive regulation of DNA-templated transcription; positive regulation of interleukin-6 production; positive regulation of interleukin-8 production; positive regulation of MAPK cascade; positive regulation of release of sequestered calcium ion into cytosol; regulation of blood coagulation; response to wounding; thrombin-activated receptor signaling pathway; anatomical structure morphogenesis; establishment of synaptic specificity at neuromuscular junction; G protein-coupled receptor signaling pathway; homeostasis of number of cells within a tissue; inflammatory response; negative regulation of glomerular filtration; negative regulation of neuron apoptotic process; and 17 more
Cellular component: caveola; cell surface; early endosome; late endosome; plasma membrane; platelet dense tubular network; extracellular region; Golgi apparatus; neuromuscular junction; postsynaptic membrane; membrane
Genetic constraint (gnomAD): Loss-of-function variants: 13 observed, 23.5 expected, observed/expected ratio (o/e) 0.55, 90% interval 0.36 to 0.88. The upper end of that interval is the gene's LOEUF score, 0.88, which puts it in group 3 of 6, group 1 being the genes least tolerant of losing a copy. Missense variants: 438 observed, 535.93 expected, observed/expected ratio (o/e) 0.82, 90% interval 0.75 to 0.88. Synonymous variants: 210 observed, 221.95 expected, observed/expected ratio (o/e) 0.95, 90% interval 0.85 to 1.06.
Homologues: Orthologues: chimpanzee F2R (99% identical), macaque F2R (98% identical), dog F2R (87% identical), pig F2R (82% identical), rat F2r (79% identical), mouse F2r (79% identical), guinea pig F2R (79% identical), rabbit F2R (69% identical), tropical clawed frog f2r (51% identical), zebrafish f2r (42% identical), zebrafish F2R (35% identical), zebrafish f2r2.1 (34% identical), and 3 more. Paralogues in human: F2RL1 (32% identical), F2RL2 (26% identical), F2RL3 (26% identical), P2RY8 (25% identical), GPR17 (23% identical), LPAR6 (23% identical), CYSLTR2 (20% identical), LPAR4 (20% identical), CYSLTR1 (20% identical), GPR18 (19% identical), GPR65 (19% identical), P2RY10 (18% identical), and 4 more.
Diseases named in the same sentence as F2R in open-access papers:
F2R is named in the same sentence as 113 diseases in open-access papers, as found by Europe PMC text mining. Sharing a sentence is not in itself a finding about the gene and the disease. The quoted sentences say what the papers report.
breast cancer (20 papers, 1999 to 2025). A primary or metastatic malignant neoplasm involving the breast. "In breast cancer, F2R also facilitates cell migration and extracellular matrix remodeling, key processes in metastasis that are known to be mediated by PAR protein family members." (PMID 40943451, 2025). "This study aims to comprehensively investigate the role of coagulation factor II thrombin receptor (F2R) in breast cancer (BC) and to evaluate its potential as a biomarker in this context." (PMID 39655193, 2024). "Gene F2R (thrombin receptor), which is differentially expressed between the investigated cancers and is also annotated in the module, is pivotal in proliferation and motility of prostate cancer cells, colon cancer cells and breast carcinoma cells." (PMID 15774002, 2005). "Other important genes include two breast cancer related genes, namely, the F2R gene, a matrix metalloprotease-1 receptor that promotes invasion and tumorigenesis of breast cancer cells; and PPAR binding protein, coactivator of ESR1 and overexpressed in breast cancer." (PMID 19458770, 2007). "Compared with normal breast epithelium cells, RFX5, VEGFA were upregulated in breast cancer cells, IKZF2, NAB1, S100B were downregulated in breast cancer cells while F2R, S1PR2 showed no significance." (PMID 40520263, 2025). "In addition, F2R, S1PR2 showed no significance between normal breast epithelium cells and breast cancer cells." (PMID 40520263, 2025).
melanoma (16 papers, 2010 to 2025). A malignant, usually aggressive tumor composed of atypical, neoplastic melanocytes. "Evidence for functional roles in cancer cells of GPCRs that are highly expressed and overexpressed in solid tumors and cancer cells include findings for PAR1/F2R in BRCA, gastric cancer, colon cancer, and melanoma cells and for PAR2/F2RL1 in melanoma, BRCA, and colon cancer cells." (PMID 31765370, 2019).
myocardial infarction (11 papers, 2010 to 2023). Gross necrosis of the myocardium, as a result of interruption of the blood supply to the area, as in coronary thrombosis. "Studies found that F2R interacts with IL-6 in the susceptibility of myocardial infarction, and coronary heart disease in hypertensive patients." (PMID 26930585, 2016).
ovarian carcinoma (11 papers, 2018 to 2025). A malignant neoplasm originating from the surface ovarian epithelium. "F2R suppression in ovarian cancer cell lines reduced tumor cell motility, invasion, spheroid formation, and metabolism and enhanced carboplatin sensitivity." (PMID 40943451, 2025). "For this purpose, intracellular F2R expression was first analyzed in ascites-derived ovarian cancer cell samples from five patients with HGSOC using flow cytometry and immunofluorescence." (PMID 40943451, 2025). "Functional in vitro studies using F2R gene knockdown in ovarian cancer cell lines significantly impaired key oncogenic processes, including cellular invasion, motility, and spheroid formation, while also sensitizing cells to carboplatin treatment." (PMID 40943451, 2025). "Collectively, these findings underscore F2R’s critical role in ovarian cancer pathophysiology and highlight its promise as a novel future therapeutic target." (PMID 40943451, 2025). "F2R is therefore a potential molecular target to further investigate its expression and functional role in ovarian cancer." (PMID 40943451, 2025). "Despite these well-known multifaceted roles of F2R in other cancers, its role in ovarian cancer remains inadequately explored." (PMID 40943451, 2025). "F2R protein expression was also significantly elevated in chemotherapy-resistant ovarian cancer tissues, further underscoring its prognostic significance." (PMID 40943451, 2025). "We investigated the coagulation factor II receptor/protease-activated receptor 1 (F2R/PAR1) as a potential diagnostic/prognostic biomarker and therapeutic target for ovarian cancer treatment." (PMID 40943451, 2025). "Our analysis confirmed elevated F2R mRNA and protein expression in ovarian cancers, notably in patients with metastatic and chemotherapy-resistant disease." (PMID 40943451, 2025). "Furthermore, F2R downregulation sensitized ovarian cancer cells to carboplatin treatment, indicating its involvement in chemotherapy resistance." (PMID 40943451, 2025). "The evaluation of novel F2R targeting strategies, using antibody-conjugated drugs or F2R ligand-decorated drug carriers, could lead to the development of effective therapeutics for patients with ovarian cancer." (PMID 40943451, 2025). "For example, PAR-2 (F2RL1) is overexpressed in some ovarian cancer tissues mainly inducing cell migration, and PAR-1 (F2R) has been found to be abundant in invasive carcinomas, but not in the healthy ovarian epithelium, driving FAK signaling and promoting cancer malignancy." (PMID 35625966, 2022).
gastric cancer (10 papers, 2011 to 2025). A primary or metastatic malignant neoplasm involving the stomach. "Similarly, in gastric cancers, F2R has been associated with angiogenesis via the activation of the Ras-associated protein 1 and mitogen-activated protein kinase (Rap1/MAPK) pathways, which contribute to tumor growth." (PMID 40943451, 2025). "However, in other cancers such as pancreatic cancer and gastric cancer, high F2R expression is associated with poor prognosis." (PMID 39655193, 2024). "Furthermore, F2R has been implicated in several cancer hallmarks, including cell migration, invasion, and proliferation, across several cancer types, including melanoma and gastric cancer." (PMID 40943451, 2025). "Previous studies have demonstrated increased F2R expression in various tumors, including lung adenocarcinoma, glioma, melanoma, and gastric cancer." (PMID 39655193, 2024). "Col1a1, fga, fgg, f2r, col3a1, and col1a2 are the important genes of this pathway, which are upregulated in gastric cancer." (PMID 35650297, 2022). "Several paired genes including (f2r, islr), (fn1, col1a1), (islr, col1a1), (islr, f2r), (pdgfrb, col1a1), (pdgfrb, f2r), and (vcan, col1a1) showed a positive correlation with each other, so that using antagonists against both of them could have a synergistic effect on the gastric cancer survival." (PMID 35650297, 2022).
atherosclerosis (9 papers, 2012 to 2025). A disease characterized by the build-up of fatty material and calcium deposition in the arterial wall resulting in partial or complete occlusion of the arterial lumen. "F2R is a member of the Proteinase-activated receptor which play critical roles in atherosclerosis." (PMID 32020855, 2020). "By virtue of its strong correlation to plasma TNF-alpha, F2R may be an important mediator of the effects of inflammation on the vessel wall, and this study further provided promising strategies of blocking F2R to the treatment of human atherosclerosis." (PMID 22761820, 2012).
COVID-19 (9 papers, 2020 to 2025). A disease caused by infection with severe acute respiratory syndrome coronavirus 2. "In ECs obtained from deceased patients who had COVID-19, the arterial subtype also predominantly expressed F2R, S1PR1, and NOS3." (PMID 39066212, 2024). "In addition, considering that THBD, PROCR, and F2R are also involved in the regulation of the inflammatory response, we suggest another important interface that supports the involvement of APC in the pathogenesis of the COVID-19-associated coagulopathy." (PMID 36560757, 2022). "In this context, autoantibodies such as ACE2-aab, AGTR2-aab, BDKRB1-aab, CXCR3-aab, MAS1-aab, CHRM5-aab, NRP1-aab, F2R-aab, STAB1-aab appeared to play a major role in stratifying COVID-19 by disease burden." (PMID 35264564, 2022). "In liver autopsy samples from patients who died because of COVID-19 complications, PC activation signaling receptors were significantly decreased compared with control as follows: 2.7-fold for S1PR1, 2.5-fold for F2R and 1.7-fold for THBD (p < 0.001), and less than 5% of cells expressed these genes." (PMID 36560757, 2022).
glioma (6 papers, 1997 to 2025). A benign or malignant brain and spinal cord tumor that arises from glial cells (astrocytes, oligodendrocytes, ependymal cells). "The expression of coagulation factor 2 thrombin receptor (F2R) was observed to be upregulated in glioma tissues, and the overexpression of F2R is associated with poor prognosis in patients with glioma." (PMID 38460946, 2024). "The overexpression of F2R could promote the proliferation and metastasis of glioma cells through EMT, thus promoting tumor growth in vivo." (PMID 38460946, 2024). "Consistent with our previous findings, the expressions of NUP107, DRAM1, RNF19A, PXDN, HEY2, F2R, and BMP2 were up-regulated in gliomas (glioblastoma multiforme + lower grade glioma)." (PMID 36245971, 2022).
prostate carcinoma (6 papers, 2005 to 2024). A carcinoma that arises from epithelial cells of the prostate gland. "F2R expression has been found to promote angiogenesis via thrombin-induced VEGF synthesis and secretion in prostate cancer." (PMID 34066023, 2021).
pancreatic cancer (4 papers, 2015 to 2024). "TFRC, a marker of human pancreatic cancer, was also expressed at a high level, as was F2R, which encodes a G-protein-coupled receptor." (PMID 25978455, 2015).
Parkinson disease (3 papers, 2024 to 2025). A progressive degenerative disorder of the central nervous system characterized by loss of dopamine producing neurons in the substantia nigra and the presence of Lewy bodies in the substantia nigra and locus coeruleus. "The results indicated that F2R mRNA expression is associated with key biological processes and pathways, including the cell cycle, ECM receptor interaction, ribosome, Parkinson’s disease, DNA replication, and oxidative phosphorylation." (PMID 39655193, 2024).
colon adenocarcinoma (2 papers, 2024 to 2025). "Analysis of large cancer datasets reveals that F2RL1 expression is among the highest in colon adenocarcinoma compared to numerous other cancer types, and significantly higher than other PAR family members (F2R/PAR1, F2RL2/PAR3, F2RL3/PAR4) within CRC tissues." (PMID 41002416, 2025).
leukemia (2 papers, 2024 to 2025). A malignant (clonal) hematologic disorder, involving hematopoietic stem cells and characterized by the presence of primitive or atypical myeloid or lymphoid cells in the bone marrow and the blood. "Most importantly, alpelisib-therapy in NSGS mice bearing nilotinib-resistant K562 cells significantly reduces leukemia burden and increases the survival time of leukemic mice, mechanistically through suppression of PI3K signaling mediators like F2R, CyclinD1 and PDGFR." (PMID 39764125, 2024).
metastatic cancer (2 papers, 2013 to 2025). A carcinoma which has spread from the original site of growth to another anatomic site. "We also provided evidence of elevated F2R protein expression in metastatic cancer tissues compared to primary tumors, suggesting its involvement in metastatic disease progression." (PMID 40943451, 2025).
stomach adenocarcinoma (2 papers, 2024). "In both in vivo and in vitro experiments, F2R was found to be significantly upregulated in gastric adenocarcinoma tissues." (PMID 38291086, 2024). "To further validate F2R expression in gastric adenocarcinoma, we performed IHC staining on human GC tissue." (PMID 38291086, 2024).
Arrhythmia (1 paper, 2020). Any cardiac rhythm other than the normal sinus rhythm. "Multiple downstream genes regulated by TBX5, F2R, and SFRP4 were involved in ICM-related diseases such as HF and arrhythmia." (PMID 32423033, 2020).
Huntington disease (1 paper, 2024). Huntington disease (HD) is a rare neurodegenerative disorder of the central nervous system characterized by unwanted choreatic movements, behavioral and psychiatric disturbances and dementia. "The results showed associations of F2R mRNA expression with DNA replication, Huntington’s disease, the JAK-STAT signaling pathway, the MAPK signaling pathway, and oxidative phosphorylation." (PMID 38291086, 2024).
liver fibrosis (1 paper, 2021). "F2r mRNA expression increased significantly at the early and progressive stages of liver fibrosis, whereas the F2rl1 mRNA level that was unchanged in acute and after 2.5-week liver injury increased at the 4th, 6th, and 7th weeks of CCl4 treatment, suggesting a delayed induction." (PMID 34566641, 2021).
metastatic disease (1 paper, 2025). "F2R is a compelling diagnostic/prognostic and therapeutic target that could be used to treat chemotherapy-resistant and metastatic disease." (PMID 40943451, 2025).